TPPP3 (tubulin polymerization promoting protein family member 3)
Diseases named in the same sentence as TPPP3 in open-access papers (continued):
Sharing a sentence is not in itself a finding about the gene and the disease.
head and neck squamous cell carcinoma (2 papers, 2020 to 2021). A squamous cell carcinoma that arises from any of the following anatomic sites: lip and oral cavity, nasal cavity, paranasal sinuses, pharynx, larynx, and salivary glands. "We conclude TPPP3 can be considered as a biomarker for predicting head and neck squamous cell carcinoma prognosis and immune infiltration." (PMID 33083464, 2020). "This study for the first time analyzed the expression and prognosis of TPPP3 in head and neck squamous cell carcinoma, unexpectedly, in contrast to the expression in other tumors." (PMID 33083464, 2020). "Our results indicate that TPPP3 expression is correlated with multiple immune cell infiltration levels in head and neck squamous cell carcinoma." (PMID 33083464, 2020). "Interestingly, in these databases, we found consistency in TPPP3 expression in head and neck squamous cell carcinoma." (PMID 33083464, 2020).
infertile (2 papers, 2014 to 2025). "Apart from this, another cytoskeletal protein, Tubulin polymerization promoting protein family member 3 (TPPP3) was also identified with decreased expression in mid-secretory phase endometrium than in early-secretory phase in these infertile women." (PMID 25405865, 2014).
lung carcinoma (2 papers, 2020 to 2023). "For example, TPPP3 knockdown has been shown to inhibit tumor growth in vitro and in vivo and induce apoptosis and cell cycle arrest in lung cancer." (PMID 36983664, 2023).
nasopharyngeal carcinoma (2 papers, 2020 to 2025). A carcinoma arising from the nasopharyngeal epithelium. "Patient survival data also indicated that a low level of TPPP3 is associated with poor prognosis for nasopharyngeal carcinoma." (PMID 41148789, 2025). "Similarly to what was found previously, all three of these genes, including TPPP3, were all downregulated in nasopharyngeal carcinoma and associated with worse survival rates." (PMID 41148789, 2025). "They found that in head and neck squamous carcinomas, specifically nasopharyngeal carcinoma, TPPP3 expression was significantly lower than that of normal tissue." (PMID 41148789, 2025). "In the present research, the expression of TPPP3 in nasopharyngeal carcinoma (NPC) tissues was detected in 57 cases of NPC and 30 cases of normal tissue by immunohistochemistry, and the relationship between TPPP3 and clinicopathological features of NPC was analyzed at the same time." (PMID 33083464, 2020).
non-small cell lung carcinoma (2 papers, 2020 to 2025). A group of at least three distinct histological types of lung cancer, including non-small cell squamous cell carcinoma, adenocarcinoma, and large cell carcinoma. "Looking at patient survival data on non-small cell lung carcinoma showed that patients with high TPPP3 expression had worse overall survival." (PMID 41148789, 2025). "Overexpression of TPPP3 in non-small-cell lung carcinoma cell lines promoted cell proliferation as well as migration and invasion." (PMID 41148789, 2025). "Furthermore, in 2016, the same group investigated the role of TPPP3 in non-small-cell lung carcinoma." (PMID 41148789, 2025). "Interestingly, in this study, Twist expression is not affected by TPPP3 knockdown like what was seen in non-small-cell lung carcinoma." (PMID 41148789, 2025).
ovarian carcinoma (2 papers, 2020). A malignant neoplasm originating from the surface ovarian epithelium. "For the gene TPPP3 there was reduced expression in ovarian clear cell carcinoma compared to healthy tissue and other ovarian cancer subtypes." (PMID 33384952, 2020).
Parkinson (2 papers, 2022 to 2025). "In relation to neurodegeneration, TPPP3 was shown to counteract alpha-synuclein aggregation in Parkinson's disease pathology and it is implicated in diabetic neuropathy." (PMID 41488750, 2025). "The next innovative goal of this project is the identification of the TPPP3 segment, which may act as a leading molecule for developing effective anti-Parkinson agents." (PMID 36230985, 2022). "TPPP3 or its selected fragments may become a leading agent for developing anti-Parkinson agents." (PMID 36230985, 2022).
sarcoma (2 papers, 2019 to 2020). A usually aggressive malignant neoplasm of the soft tissue or bone. "It is noteworthy that EWS/ATF1induced sarcomas from Tppp3-expressing neural crest-derived cells in peripheral nerves." (PMID 31488818, 2019). "We found that Tppp3-expressing cells can give rise to sarcomas and early sarcoma lesions often express S100, which suggests that Tppp3/S100-expressing neural crest-derived cells in peripheral nerves are a cell of origin for EWS/ATF1-induced sarcomas." (PMID 31488818, 2019). "Using this unique cancer model, we determined Tppp3-expressing peripheral nerve cells as an origin of EWS/ATF1-induced sarcomas, provided insights into the cell type specificity for cancer development." (PMID 31488818, 2019). "Considering the heterogeneous nature of Tppp3-expressing cells, it seems technically difficult to isolate Tppp3-expressing cells that give rise to the sarcoma." (PMID 31488818, 2019). "We identify Tppp3-expressing cells in peripheral nerves as a cell-of-origin for these sarcomas." (PMID 31488818, 2019). "To further confirm that Tppp3-expressing cells give rise to sarcomas, we also generated mice harboring Tppp3-CreERT2 allele and Rosa26-loxP-stop-loxP (LSL)-EWS/ATF1 allele (Rosa26Stop-E/A/Tppp3CreERT2) in which EWS/ATF1 can be induced in Tppp3-expressing cells upon tamoxifen treatment." (PMID 31488818, 2019). "Collectively, we propose that Tppp3-expressing and Sox10/Krox20-negative neural crest-derived peripheral nerve cells are a cell of origin for EWS/ATF1-induced sarcomas, at least in this transgenic mouse model." (PMID 31488818, 2019). "Taken together, we propose that Tppp3-expressing and Sox10-negative neural crest-derived peripheral nerve cells are a cell of origin for EWS/ATF1-induced sarcomas." (PMID 31488818, 2019). "Collectively, we concluded that Tppp3-expressing cells, but not Sox10-expressing cells, are a cell of origin for EWS/ATF1-induced sarcomas." (PMID 31488818, 2019).
sarcopenia (2 papers, 2024 to 2025). Progressive decline in muscle mass due to aging which results in decreased functional capacity of muscles. "Among them, MYH8, HOXB2, C1QA, CDKN1A, and SLC38A1 are associated with sarcopenia, and in this study, LGR5, SERPINA5, and TPPP3 genes were found to be associated with Sarcopenia for the first time." (PMID 38229116, 2024). "In patients with sarcopenia, the expression of TPPP3, C1QA, LGR5, MYH8, and CDKN1A genes are upregulated, and the expression of SLC38A1, SERPINA5, and HOXB2 genes are downregulated." (PMID 38229116, 2024).
Allergy (1 paper, 2022). An allergy is an immune response or reaction to substances that are usually not harmful. "This protein group includes proteins involved in cell stress response (HSPB1), mucosal protection and allergy (MUC1), complement activation (CD55) and actin polymerization (CAPG, APRT, TPPP3)." (PMID 35590254, 2022).
asthma (1 paper, 2022). "Commonly downregulated to PTSD and severe asthma were ORMDL3 (2.2E-2, 1.9E-3, 2.7E-3, 3.9E-3), PTP4A3 (2.6E-3, 2.3E-2, 4.5E-3, 5.2E-3), SHISA4 (1.1E-2, 4.4E-2, 9.8E-3, 6.2E-3), and TPPP3 (2.2E-2, 1.1E-2, 3.1E-3, 2.7E-2)." (PMID 36206293, 2022).
breast invasive carcinoma (1 paper, 2020). "The TPPP3 expression was significantly decreased in HNSC, bladder urothelial carcinoma (BLCA), breast invasive carcinoma (BRCA), kidney chromophobe (KICH), kidney renal papillary cell carcinoma (KIPC), lung adenocarcinoma (LUAD), and lung squamous cell carcinoma (LUSC)." (PMID 33083464, 2020).
cholangiocarcinoma (1 paper, 2020). A carcinoma that arises from the intrahepatic biliary tree (intrahepatic cholangiocarcinoma) or from the junction, or adjacent to the junction, of the right and left hepatic ducts (hilar cholangiocarcinoma). "However, compared with adjacent normal tissues, the TPPP3 expression was significantly higher in cholangiocarcinoma (CHOL) and kidney renal clear cell carcinoma (KIRC)." (PMID 33083464, 2020).
coronary heart disease (1 paper, 2022). "Significantly upregulated were gene regulators of VSMC differentiation, triggers of cell apoptosis, inflammation and coronary heart disease markers (Itih4, Tppp3, Slc25a39, CD44) in parallel to atheroprotective genes such as Morf4l2." (PMID 35163719, 2022).
fibrosis (1 paper, 2023). the formation of excess fibrous connective tissue in an organ or tissue in a reparative or reactive process. "Here, using a fibrosis mouse model and clinical samples of human Dupuytren’s contractures, we demonstrate that the activation of Wnt/β-catenin signalling in Tppp3-positive cells in the dermis of the paw is associated with the development of fibrosis." (PMID 37980373, 2023).
glioma (1 paper, 2023). A benign or malignant brain and spinal cord tumor that arises from glial cells (astrocytes, oligodendrocytes, ependymal cells). "IHC and IF were performed to further confirm the expression of TPPP3 in different grades of glioma tissue and normal brain tissue." (PMID 37863960, 2023). "In this study, we first detected the expression of TPPP3 in various grades of glioma tissues." (PMID 37863960, 2023). "Our data indicated that TPPP3 may promote the migration, invasion, proliferation and inhibit apoptosis of glioma cells via Snail1 by accelerating EMT." (PMID 37863960, 2023). "We performed surgical separation of glioma and normal brain tissues from 81 patients, and used real-time fluorescence quantitative PCR to quantitatively analyze the mRNA abundance of TPPP3 in randomly selected surgically separated tissues and normal brain tissues." (PMID 37863960, 2023). "Here, we investigated the role and application value of TPPP3 in gliomas and found that the expression of TPPP3 in glioma was higher than that in normal brain tissue (NBT), and increased with the grade of glioma." (PMID 37863960, 2023). "It was found that the expression of TPPP3 in gliomas was higher than that in normal brain tissue (NBT), and it became more pronounced as the grade of gliomas increased." (PMID 37863960, 2023).
hepatocellular carcinoma (1 paper, 2025). A malignant tumor that arises from hepatocytes. "Clinical data support these findings, demonstrating that high TPPP3 expression in hepatocellular carcinoma patients correlates with worse overall survival." (PMID 41148789, 2025). "TPPP3 allowed hepatocellular carcinoma cells to withstand fluid shear stress better than TPPP3 knockdown cells, making them more viable during metastasis." (PMID 41148789, 2025). "In hepatocellular carcinoma, TPPP3 is involved in a more structural context." (PMID 41148789, 2025).
lentivirus infection (1 paper, 2020). Virus diseases caused by the Lentivirus genus. "The protein levels of TPPP3 were efficiently decreased after the lentivirus infection." (PMID 33082910, 2020).
Miscarriage (1 paper, 2023). A pregnancy that ends at a stage in which the fetus is incapable of surviving on its own, defined as the spontaneous loss of a fetus before the 22th week of pregnancy. "Interestingly, the expression levels of TPPP3 and HSD17B2 also decreased in the decidual tissues of patients with miscarriage." (PMID 37583433, 2023).
myopia (1 paper, 2024). "Eight pairs (protein-coding genes TOM1L2, MXRA7, RHPN2, and HINT1 for senile cataract, WARS1 and TDRD7 for AMD, STAT6 for myopia, and TPPP3 for DR) are newly reported in this study." (PMID 39408566, 2024).
pancreatic ductal adenocarcinoma (1 paper, 2025). An infiltrating adenocarcinoma that arises from the epithelial cells of the pancreas. "Pancreatic ductal adenocarcinoma tumors also showed worse overall survival with lower TPPP3 expression." (PMID 41148789, 2025).
Primary Immunodeficiency (1 paper, 2020). "The pathways closely related to the low expression of TPPP3 are “Antigen Processing and Presentation,” “Primary Immunodeficiency,” and so on." (PMID 33083464, 2020).
squamous carcinoma (1 paper, 2022). "Interestingly, several genes found to be differentially enriched in the BC-2 subpopulation, such as Tppp3, Tnfrsf12a, and Cav1 have been associated with severity or aggressiveness of squamous carcinoma in various organs." (PMID 36178196, 2022).
steatosis (1 paper, 2025). Increased lipid within the cytoplasm of cells. "Histopathological evaluation via H&E staining confirmed MASLD-associated steatosis and fibrosis, while IHC revealed that TPPP3 and COL10A1 localized to fibrotic septa and peri-sinusoidal regions, with staining intensities strongly correlated with fibrosis severity." (PMID 40380802, 2025).
tumor (16 papers, 2011 to 2025). "In vitro and in vivo experiments showed that loss of TPPP3 expression significantly decreased cell proliferation and tumor growth." (PMID 41148789, 2025). "The angiogenic function of Tppp3+ monocyte is mainly supported by high expression of Anxa1 and Anxa2, encoding proteins involved in tumor angiogenesis and metastasis." (PMID 37483625, 2023). "Interestingly, elevated levels of TPPP3 expression were associated with certain immune cell infiltration into the tumor." (PMID 41148789, 2025). "We obtained results on the correlation between TPPP3 expression and marker genes of tumor infiltration-associated immune cells, including CD8+T cells (CD8A and CD8B), B cell (CD19 and CD79a), and Myeloid dendritic cell (HLA-DPB1, HLA-DQB1, HLA-DRA, HLA-DPA1, CD1C, NRP1, and ITGAX)." (PMID 33083464, 2020). "Silencing of circMUC16 increased miR-1182 and decreased TPPP3 expression, exhibiting anti-tumor effects." (PMID 41148789, 2025). "They later expanded on this initial study in Lewis lung carcinoma, finding that TPPP3 depletion also inhibited tumor growth as well as metastasis." (PMID 41148789, 2025). "Studies have revealed that TPPP3 gene can inhibit cell proliferation, induce apoptosis and cell cycle arrest, and inhibit tumor growth." (PMID 37583433, 2023). "Human monocyte cluster 0 expressed the highest signatures of mouse Tppp3+ monocytes and specially appeared in the tumor group." (PMID 37483625, 2023). "The expression levels/functions of TPPP3 in tumor/cancer cells are tangled; it is largely dependent on the types of the tumors." (PMID 36230985, 2022). "A growing number of researchers have been exploring the relationship between TPPP3 and tumor development in recent years." (PMID 33083464, 2020). "Besides, the TPPP3 expression may help regulate tumor-associated CD8 + T cells, DC cells in HNSC." (PMID 33083464, 2020). "One such gap is the discrepancy seen in the role TPPP3 plays in cancer, whether it be oncogenic or tumor suppressive." (PMID 41148789, 2025). "In addition, they found that TPPP3 expression also correlated with levels of immune cell infiltration in the tumor." (PMID 41148789, 2025). "Then, we performed immunofluorescence staining on the normal lung, primary tumor, and metastatic lung sections using the markers of Tppp3+ monocytes (LY6C and TPPP3), Isg15+ macrophages (F4/80 and ISG15), Ifit3+ neutrophils (MPO and IFIT3), and Il12b+ DCs (CD11c and IL12B)." (PMID 37483625, 2023). "Moreover, the down-regulation of TPPP3 at transcriptional levels inhibits tumor cell proliferation, migration and lung cancer growth in vivo." (PMID 36230985, 2022). "In addition, to further understanding of TPPP3 expression in head and neck tumors, we also performed immunohistochemistry on clinical NPC specimens and validated tumor and normal tissue TPPP3 mRNA expression in two GEO NPC datasets." (PMID 33083464, 2020). "Depletion by RNAi or by shRNA inhibited tumor cell proliferation, migration and invasion; inhibited lung cancer growth in vivo; and survival rate was lower in patients with high expression of TPPP3." (PMID 32033023, 2020). "We found that using different databases, TPPP3 expression levels differed among different tumor types, which may be due to the data collection method and the different biological characteristics of TPPP3." (PMID 33083464, 2020). "In contrast to the issue presented in relation of TPPP/p25, higher mRNA and/or protein expression of TPPP3 was found in tumor cells in comparison to normal ones in most cases investigated up to now, for example, in various lung, colorectal and ovarian tumors and in HeLa cells." (PMID 32033023, 2020). "In addition, we also examined the relationship between TPPP3 and tumor-infiltrating immune cells in HNSC through the Tumor Immunity Estimation Resource 2.0(TIMER 2.0)." (PMID 33083464, 2020). "Therefore, we shifted the research focus of TPPP3 to research on tumor immune infiltration." (PMID 33083464, 2020).
tumor (continued). "CD24, CLDN3, WFDC2, and TACSTD2 genes were present in all the tumour clusters of all samples, and the genes C1orf194, C20orf85, MS4A8, ODF3B, RSPH1, and TPPP3 appear to be co‐expressed." (PMID 41160707, 2025). "A number of data suggest higher TPPP3 expression, in contrast to TPPP1, in tumor cells of various lung, colorectal, ovarian tumors and clear cell sarcoma than that of normal ones." (PMID 36230985, 2022). "As reported, TPPP3, DOCK2, and EIF3H act as oncogenes by suppressing apoptosis of cancer cells, while RNF128, DAPK1, and SYT7 function as tumor suppressors by promoting apoptosis of many types of cancer cells." (PMID 33509274, 2021). "The related pathways involved in TPPP3 were analyzed by gene-set enrichment analysis (GSEA), and the correlation between TPPP3 and immune infiltration was studied by Tumor Immune Estimation Resource2.0 (TIMER 2.0)." (PMID 33083464, 2020). "The results from MMTV-PyVT mice show that TPPP3+ monocytes, ISG15+ macrophages, IFIT3+ neutrophils, and IL12B+ DCs are mainly present in the tumor-reprogrammed lung microenvironment, and the metastasis-associated myeloid subpopulations are validated at the protein level." (PMID 37483625, 2023). "TPPP3, a member of TPPP family, has been confirmed to be involved in the regulation of these malignant behavior transformation in tumor cells in a number of tumor studies." (PMID 37863960, 2023). "To understand the differences in TPPP3 expression between human tumor and nontumor tissues, we utilized the Oncomine database to analyze the expression levels of TPPP3 in multiple cancer types and different tumors and normal tissues." (PMID 33083464, 2020). "Whether TPPP3 is a key factor in mediating CD8 + T cell, DC, and tumor metastasis need further research." (PMID 33083464, 2020). "The expression of CD24 and TPPP3 in the controls is not surprising, and the expression of other tumour biomarkers in control 3 could be due to a previous mechanical obstruction of the fallopian tube." (PMID 41160707, 2025). "Although TPPP3 has not been extensively studied, according to the available data, it is found that the expression level of TPPP3 was increased in some tumors and correlated with tumor proliferation." (PMID 33083464, 2020).